IL7 (interleukin 7)
Diseases named in the same sentence as IL7 in open-access papers (continued):
Sharing a sentence is not in itself a finding about the gene and the disease.
viral infection (continued). "There are multiple sources for circulating IL-7 during viral infections including lymphoid organs, epithelial cells and recently the liver was identified as a major source of IL-7." (PMID 22529911, 2012). "Of these, STAT4 transduces IL12 and IFN-A cytokine signals in T cells and monocytes whereas IL7 is critical for proper T cell response and expansion during viral infection." (PMID 21901105, 2011). "Multiple studies in both human and murine models have shown that antigen‐specific CD8+ T cells derived from chronic viral infections often fail to develop into long‐lived memory cells, even after viral clearance, and lack the capacity for homeostatic proliferation in response to IL‐7 and IL‐15." (PMID 41410180, 2025). "How IL-7 shapes CD8 T cell responses during an acute viral infection is less understood." (PMID 34997007, 2022). "Viral infections of intestinal cells induce IFNβ1 and subsequently IL7." (PMID 34045640, 2021). "This, combined with our observation that viruses can induce IL7 through IFNβ1, might also indicate that viral infections can affect the severity of IBD." (PMID 34045640, 2021). "In addition, we show that viral infections of intestinal organoids induce IFNβ1 that, via subsequent autocrine stimulation, induces IL7 expression in enterocytes." (PMID 34045640, 2021). "Of note, the use of IL-7 as therapy in bacterial and viral infections is under investigation." (PMID 33584648, 2020). "Hence, it will be important to characterize the effects of additional TLR signals and different types of viral infections on IL-7 expression in salivary gland cells." (PMID 24147035, 2013). "It is unknown whether this is the result of viral infection, antigen stimulation or ongoing ligand stimulation by elevated levels of IL-7." (PMID 22348045, 2012). "This may be secondary to transcriptional down-regulation, viral infection, antigen stimulation, or IL-7-driven down-regulation promoting endocytosis and/or shedding." (PMID 22348045, 2012). "Interestingly, IL-7 shows proven efficacy as an antiviral agent and has been shown to restore lymphocyte counts and functional activity, leading to decreased viral load and clinical improvement in several life-threating viral infections." (PMID 36975498, 2023). "Hence, it is likely that the observed increase in IL-7 may have implications with control of viral infections." (PMID 36405584, 2022). "However, the extent to which IL-7 regulates CD8 T cell response to acute viral infections is unknown." (PMID 34997007, 2022). "Induced by a series of other cytokines as IL1A (IL1A fold regulation = 2.99), IL1B (IL1B fold regulation = 10.76), IL7, TNF (TNF fold regulation = 2.39), LPS or viral infections, CCL5 behaves like a proinflammatory cytokine." (PMID 40149697, 2025). "Elevated release of interleukin(IL)-6, IL-7, and tumor necrosis factor (TNF) have been recorded as the consequence of innate immune response upon the viral infection." (PMID 37456016, 2023). "Treatment with IL-7 appears to reduce the rate of progression of HIV, HBV, and HCV viral infections." (PMID 36405584, 2022). "Irreversible down-regulation of IL-7Rα also occurs in functionally “exhausted” T cells that accumulate during persistent viral infections, such as HIV or LCMV and, interestingly, high levels of IL-7 can be detected in the serum of AIDS patients." (PMID 22102903, 2011). "Since these sIFs have strong connections to inflammatory diseases and viral infections, it is unsurprising to see elevated fecal levels in PLWH but levels of four sIFs (GM-CSF, ICAM-1, IL-7 and IL-12/23) were similarly elevated in MSM-SN compared to non-MSM-SN." (PMID 36605218, 2022). "Moreover, increased plasma IL-7 levels can also be observed during viral infection in non-lymphopenic individuals (and unpublished data), suggesting a role in the development of immune responses." (PMID 22529911, 2012).
viral infection (continued). "The sorted cells were subsequently cultured with an integrase inhibitor, preventing new rounds of virus infection, and treated with 100 U/mL of IFN (α, β, ε, ω, λ1 or λ3) in the presence or absence of anti-CD3/CD28+IL-7+IL-2." (PMID 32109259, 2020). "This is not surprising as IL-15, in concert with IL-7, acts as a regulator of CD8+ T cells, whose primary role is in the immune response to viral infection, and not bacterial infection." (PMID 21711552, 2011).
lung carcinoma (39 papers, 2008 to 2026). "Although IL-7 levels were comparable between MPE of lung cancer patients and pleural effusions, higher IL-7 concentrations were associated with poorer survival outcomes in lung cancer patients with MPE." (PMID 40959273, 2025). "IL-6, IL-7, IL-10, and IL-17A levels were elevated in the plasma of lung cancer patients as compared to those in healthy controls; thus, indicating higher concentrations of inflammatory mediators in patients." (PMID 40040705, 2025). "Research in mouse models of intestinal and lung cancer suggests that IL-7 enhances CD8+ T cell infiltration and suppresses myeloid-derived suppressor cells, boosting the efficacy of chemotherapy and immunotherapy." (PMID 38779093, 2024). "In a murine lung cancer model, IL‐7 + sCD127 treatment enhanced antigen presentation, T‐cell activity and inflammation in the tumor microenvironment which reduced tumor burden and improved survival compared with IL‐7 alone." (PMID 34525268, 2021). "Interleukin-7 receptor (IL7R) is the receptor of IL-7, and the IL-7/IL-7R interaction seems to have a two-sided effect in lung cancer." (PMID 35069695, 2021). "In parallel, they showed, by in situ analysis of human NSCLC, that overexpression of IL-7/IL-7R and mTOR plays an important role in decreasing lung cancer cell autophagy and increases tumor development." (PMID 33066678, 2020). "By limiting p27kip, IL-7 was shown to promote lung cancer proliferation and accelerate bladder cancer invasion and migration." (PMID 33816214, 2020). "IL-7 can directly abrogate the Treg-mediated suppression of effector T cell proliferation and decrease the population of Tregs in the lung cancer model." (PMID 32698361, 2020). "The effect of IL-7 on chemotherapy resistance of NSCLC was studied using two lung cancer cell lines, A549 and its corresponding DDP-resistant cell line A549/DDP." (PMID 31915416, 2019). "By inducing cyclin D1 upregulation via the c-Fos/c-Jun pathway, IL-7 promotes the proliferation of lung cancer cells." (PMID 31061414, 2019). "It has also been shown that intratumoral IL-7 injection transduced dendritic cells resulting in complete tumor regression in a murine lung cancer; IL-7 administration increased sensitization of metastatic nodules to radiofrequency thermal ablation in lungs." (PMID 31915416, 2019). "In lung cancer, IL-7 protein expression has correlated with increased lymphovascular density, lymph node metastases, advanced clinical stage, VEGF-D, and cyclin D expression and has been identified as a potent marker for bone metastasis." (PMID 27866242, 2017). "This increase of serum IL-7 is at least in part dependent on IL-7 production by tumor cells as demonstrated in a human-in-mice model of bone metastasis from lung cancer." (PMID 26064994, 2015). "IL-7 can directly abrogate the Treg-mediated suppression of effector T cell proliferation and decrease the population of Treg in spleen of lung cancer model." (PMID 25955647, 2015). "Likely, it was shown that c-Fos and c-Jun dimer promotes the interleukin-7-induced lymphangiogenesis in lung cancer by upregulating VEGFD expression." (PMID 25260594, 2014). "Study on lung cancer cells provided evidence that IL-7/IL-7R is well correlated with VEGF and induce its upregulation." (PMID 24348676, 2013). "The aim of this study is to explore the expressions of IL-7 and IL-7R in lung cancer and the relationship between them with lymph node metastasis and prognosis in non-small cell lung cancer (NSCLC)." (PMID 21159243, 2010).
lung carcinoma (continued). "Studies on the impact of CXCR3 ligand in IL‐7/IL‐7Rα‐Fc–mediated antitumor activity revealed that when treating mice with lung cancer using IL‐7/IL‐7Rα‐Fc, it raised the levels of chemokine ligands CXCL9 and CXCL10, IFNγ, and IL‐12, but it reduced the levels of IL‐10 and TGF‐β." (PMID 39083441, 2025). "Indeed, IL-7 activates PI3 K/Akt/mTOR signaling pathway via Beclin1 to regulate autophagy in lung cancer cells." (PMID 33773561, 2021). "Therefore, the inconsistent functioning of IL-7 in lung cancer is attributable to the discrepancy of dosage, administration, and combination schedule." (PMID 31915416, 2019). "Interestingly, intratumoral injection with adenoviral IL-7 transduced DCs resulted in complete tumor regression in a murine lung cancer model." (PMID 25955647, 2015). "We asked whether pleural fluid IL‐7 also had prognostic value in PE secondary to lung cancer." (PMID 36054746, 2022). "The xenograft model of the DDP-resistant human lung cancer cell line A549/DDP was established, and nude mice were treated with IL-7 (2 μg/injection, twice a week) and DDP (5 mg/kg, twice a week)." (PMID 31915416, 2019). "Functionally, IL7 has been shown to induce expression of VEGF-D and cyclin D in A549 cells and promote proliferation and lymphangiogenesis of lung cancer xenograft tumors." (PMID 27866242, 2017). "The utility of the chimeric homeostatic cytokine, IL-7/IL-7Rα-Fc, partly restored APC activities in lung cancer, with a stronger capacity to process and present antigens to activate CD8+ T cells." (PMID 25955647, 2015). "The expressions of IL-7 and IL-7R in 95 cases of NSCLC were detected with immunohistochemistry method and the relationship between IL-7 and IL-7R and their impact on lung cancer patients' outcomes were analyzed." (PMID 21159243, 2010). "Similarly, IL-7 enhances bladder cancer invasion through NF-κB-mediated MMP-9 expression and promotes lung cancer proliferation by upregulating cyclin D1 via the c-FOS/c-Jun pathway." (PMID 41596598, 2026). "Moreover, previous studies have shown that various inflammatory factors, such as IL-7, induce VEGF-D expression and promote lymphangiogenesis via the c-Fos/c-Jun pathway in lung cancer." (PMID 25891418, 2015). "Evidence suggests that cytokines such as interleukin-1β (IL-1β), IL-6, interleukin-7 (IL-7), interleukin-8 (IL-8), interleukin-11 (IL-11), tumor necrosis factor-alpha (TNF-α), TGF-β, and C-C motif chemokine ligand 12 (CCL12) play significant roles in the bone metastasis of lung cancer." (PMID 38571500, 2024). "However, we observed that high IL‐7 levels in PEs were associated with shorter survival of MPM patients, but not of lung cancer patients." (PMID 36054746, 2022). "Unlike in breast and lung cancers, IL-7 did not stimulate proliferation of colon-cancer cells." (PMID 31185636, 2019). "Finally, the study of the expression of IL‐7 in pleural effusions (PEs) showed a significant higher level of IL‐7 in MPM PE compared to benign PE and that high IL‐7 level in the PE was associated with lower survival of patients in MPM but not in lung cancer patients." (PMID 36054746, 2022).
HIV-1 infection (35 papers, 2004 to 2026). The type species of lentivirus and the etiologic agent of acquired immunodeficiency syndrome (AIDS). "Five biomarkers (ITAC, IL-8, IL-7, TNFα, and Fractalkine) were identified as the most significant contributors to the signature associated with future HIV-1 infection." (PMID 33731158, 2021). "SAMHD1 inactivation also clearly plays a role in IL-7-treated resting T cells, which are more susceptible to HIV-1 infection." (PMID 31042779, 2019). "This phenomenon suggests that the permissive state for HIV-1 infection induced by IL-7 is associated with an increased responsiveness to activation via CD3 and CD28." (PMID 14737186, 2004). "The effects of IL-7 on thymopoiesis may be dependent, on one hand, on the underlying disease (HIV-1 infection, cancer and chemotherapy) and, on the other hand, on the duration of cytokine therapy." (PMID 24853554, 2014). "Plasma IL-7 levels are elevated in untreated HIV-1 infection and subsequently restored along with IL-7Rα expression on αβ T cells during ART50." (PMID 39149467, 2024). "Previous work also showed that IL-7 induced NFAT activity is a supplementary mechanism through which IL-7 can affect HIV-1 infection in naïve T cells." (PMID 31042779, 2019). "Dysregulated IL-7/IL-7R signaling in HIV-1 infection has been proposed by several groups as a critical link between HIV-1-driven immune activation and bystander CD4+ T cell loss." (PMID 31507594, 2019). "In this study, two different latency models based on CCL19 or IL-7 treatment before HIV-1 infection were used." (PMID 28539614, 2017). "The effect of different concentrations of MVC in the reactivation of latent NL4.3-wt HIV-1 strain was studied in CD4+ primary T lymphocytes treated with CCL19 or IL-7 before HIV-1 infection." (PMID 28539614, 2017). "Viral reactivation mediated by MVC was studied in two different resting primary T cell models based on CCL19 or IL-7 exposure before HIV-1 infection." (PMID 28539614, 2017). "Because of its favorable characteristic of inducing little homeostatic proliferation while efficiently enhancing HIV-1 infection, IL-4 is a useful alternative to IL-7 in such studies." (PMID 25330112, 2014). "Our results demonstrate that exposure of cervico-vaginal and lymphoid tissues ex vivo to IL-7 at concentrations comparable with those found in semen of HIV-1-infected individuals facilitates HIV-1 infection." (PMID 23408885, 2013). "Here, we investigated the effect of IL-7 on HIV-1 infection of human cervico-vaginal and lymphoid tissue ex vivo." (PMID 23408885, 2013). "To date, however, IL-7 has been tested exclusively in patients with chronic HIV-1 infection, while it appears that the immune system is irreparably damaged during acute primary infection, within the first few weeks after encountering the virus." (PMID 22511868, 2012). "In contrast, HIV-1 infection is associated with stage-specific progressive decreases in the FRC network and thus the available source of IL-7." (PMID 22241988, 2012). "Previous studies have shown a significant increase of IL-7 level also in lymphopenic states due to HIV-1 infection and currently there are ongoing clinical investigations on IL-7 as a potential anti-HIV therapy." (PMID 22591651, 2012). "Our findings also suggest the potential clinical benefit of complementing IL-7 treatment during HIV-1 infection in the restoration of naïve T cell population." (PMID 22241988, 2012). "Although the effects of IL-7 on MAIT cells have been clear for some time, it is unknown whether IL7RA polymorphisms affect MAIT cell phenotype and function in health and during HIV-1 infection." (PMID 36341446, 2022). "- HIV-1 infection disrupts IL-7/IL-7R signaling and CD4+ T cell memory formation." (PMID 31507594, 2019). "We conclude that IL-7, a cytokine whose level is elevated during HIV-1 infection, may have a role in increased expression of B cell costimulatory molecules on Tfh cells and lead to abnormal B cell differentiation." (PMID 28473831, 2017).
HIV-1 infection (continued). "An increased serum IL-7 concentration was reported during HIV-1 infection [reviewed in Ref." (PMID 28473831, 2017). "HIV-1-latency models based on CCL19 or IL7 treatment, before HIV-1 infection were used." (PMID 28539614, 2017). "Indeed, many studies have shown that plasma levels of IL-7 actually increase in advanced HIV-1 infection." (PMID 27011165, 2016). "IL-7 plays a central role in T cell development and homeostasis, and it is currently being evaluated as a treatment for severe lymphopenia in lymphoablative chemo- and radiotherapies and in the course of HIV-1 infection." (PMID 23408885, 2013). "Moreover, in the course of HIV-1 infection the seminal plasma concentration of IL-7 is increased compared with that in uninfected individuals." (PMID 23408885, 2013). "What are the mechanisms of IL-7-mediated facilitation of HIV-1 infection?" (PMID 23408885, 2013). "Moreover, when tissues were exposed to IL-7 prior to HIV-1 infection only, subsequent HIV-1 replication was enhanced." (PMID 23408885, 2013). "In our previous studies we showed that elevated IL-7 levels may not only support T cell activation during HIV-1 infection but can also contribute to T cell depletion through CD95 mediated apoptosis." (PMID 22194871, 2011). "Data showing an increase of viral replication kinetics after inhibition of FOXO1 in quiescent T cells treated with IL-7 now suggest that this molecule may be another molecular switch controlling HIV-1 infection and participating in the effects of this cytokine on the biology of HIV-1 in T cells." (PMID 31042779, 2019). "Thus, IL-7 might be an effective adjuvant therapy in acute HIV-1 infection, which can protect the pool of CD4+ T cells before it is irreversibly compromised by the action of the virus." (PMID 22511868, 2012). "Although treatment with interleukin-7 (IL-7) was shown to transiently expand the naïve and memory T-cell pools in patients with chronic HIV-1 infection receiving antiretroviral therapy (ART), it is uncertain whether a full immunologic reconstitution can be achieved." (PMID 22511868, 2012). "We followed HIV-1 infection of primary resting CD4 T cells and found that HIV-1 infection of IL-7–treated blood resting CD4 T cells down-regulates PSGL-1 exclusively in the HIV-1–positive cell population." (PMID 32273392, 2020). "As HIV-1 infection advances, collagen deposition increases and the FRC network is destroyed, which decreases the amount of IL-7 available to support T cell survival." (PMID 22241988, 2012). "Our data provide a scientific basis for the clinical evaluation of IL-7, in combination with ART, for the treatment of acute primary HIV-1 infection." (PMID 22511868, 2012). "Understanding intricate utilization of IL-7 in reconstituting MAIT cells and enhancing their functions may ultimately benefit the host defense during HIV-1 infection." (PMID 36341446, 2022). "Furthermore, under hypoxic conditions, an interleukin-7 (IL-7)-induced increase in the expression of the GLUT1 has been observed, which leads to an increase in glucose uptake favoring HIV-1 infection." (PMID 34360716, 2021). "Given that IL-7 signaling drives optimal mucosal ILC2 and ILC3 homeostasis in mice, it will be interesting to determine whether HIV-1 infection regulates IL-7 production in mucosal tissues to circumvent tissue-resident lymphocyte responses." (PMID 30893756, 2019). "Our observation that γc cytokines, specifically IL-2, IL-7, IL-15, and IL-21 were potent inducers of Tim-3 expression on T cells in the antigen-independent manner in HBV infection were consistent with the role of these cytokines in HIV-1 infection." (PMID 28401068, 2017). "However, our results show that levels of IL7 and CCL21 actually decrease in lymph nodes under advanced HIV-1 infection, which is consistent with our perspective that peripheral recovery of CD4+ T cells does not represent their recovery in lymph nodes." (PMID 27011165, 2016).